SLC45A2 (solute carrier family 45 member 2)
Diseases named in the same sentence as SLC45A2 in open-access papers (continued):
Sharing a sentence is not in itself a finding about the gene and the disease.
albinism (continued). "Comparisons of the SNP positions with a list of genes that are known to be involved in albinism showed that SLC45A2 (solute carrier family 45 member 2) on BTA20: 39,829,673–39,867,694 bp was located within the borders of the largest stretch of extended homozygosity." (PMID 28982372, 2017). "Other albinism classes are: OCA2 caused by deletion or loss of activity of the melanosomal P-protein (OCA2 gene); OCA3 attributable to mutations in TYRP1; OCA4 due to loss of SLC45A2; and OCA5 which is linked to chromosome 4q24, with the responsible gene yet to be characterized." (PMID 32966289, 2020). "As the major enzymes participated in mammals albinism, TYR, TYRP1, OCA2 and SLC45A2 also exhibited down regulation in albino pigmented P. olivaceus individuals." (PMID 28777813, 2017). "In the present study, we analyzed 122 heterozygous patients with albinism either by whole genome sequencing or by the use of our next-generation sequencing panel that includes the entire sequence of the TYR, OCA2, SLC45A2, GPR143 and HPS1 genes (exons, introns, flanking sequences)." (PMID 39201349, 2024). "Genetic analysis revealed seven coding variants in the cohort that were presumed to be albinism-causing and, to the authors’ knowledge, have not previously been reported: three in TYR, one in OCA2, one in TYRP1, one in SLC45A2, and one in GPR143." (PMID 38441889, 2024). "Autosomal recessive ocular albinism (AROA) is a term that has been used for patients with albinism with an ocular phenotype caused by mutations in TYR, OCA2, TYRP, SLC45A2, SLC24A5, or LRMDA (OCA1-7), but without a clearly defined boundary between calling a phenotype OCA or AROA." (PMID 38555393, 2024).
oculocutaneous albinism (20 papers, 2010 to 2025). Oculocutaneous albinism (OCA) describes a group of inherited disorders of melanin biosynthesis characterized by a generalized reduction in pigmentation of hair, skin and eyes and variable ocular findings including nystagmus, reduced visual acuity and photophobia. "For instance, we detected frameshift and missense variants in MOCOS and SLC45A2 that are associated with recessive xanthinuria and oculocutaneous albinism, respectively." (PMID 31914939, 2020). "Analysis of sequence data from a Braunvieh animal with oculocutaneous albinism revealed two non-synonymous SNPs in the SLC45A2 gene on BTA20 that were both confirmed as candidate causal mutations by targeted genotyping." (PMID 28982372, 2017). "Two non-synonymous SNPs at positions 39,829,806 bp (G/A; R45Q) and 39,864,148 bp (C/T; T444I) in the SLC45A2 gene on BTA20 were identified as candidate causal mutations for oculocutaneous albinism in two Braunvieh calves." (PMID 28982372, 2017). "In this paper, we present a case of oculocutaneous albinism in two related Braunvieh calves that is most probably caused by a mutation in the SLC45A2 gene on BTA20." (PMID 28982372, 2017). "Mutations in TYR, OCA2, TYRP1, and SLC45A2 are mainly responsible for causing oculocutaneous albinism." (PMID 25093188, 2014). "Similarly, mutations in the bovine SLC45A2 gene have been shown to cause oculocutaneous albinism, while the KITLG gene has been associated with the roan coat type in cattle." (PMID 38571912, 2024). "SLC45A2 mutations and polymorphisms cause oculocutaneous albinism (OCA) and pigmentation variation." (PMID 37255601, 2023). "Slc45a2 is involved in developmental pigmentation and associated with oculocutaneous albinism." (PMID 25790447, 2015). "Oculocutaneous albinism (OCA) is a genetic disorder caused by mutations in genes involved in melanin synthesis, including Tyr (OCA-1), Oca2 (OCA-2), Tyrp1 (OCA-3), and Slc45a2 (OCA-4)." (PMID 40286213, 2025). "Genetic defects in expression of some melanogenic enzymes (TYR, TYRP1) or other melanin synthesis regulators (P protein, SLC45A2,) result in oculocutaneous albinism (OCA1-OCA4) and visual function impairment, demonstrating the importance of melanin for proper ocular function." (PMID 35682684, 2022). "Inactivating mutations in these genes have been reported to cause oculocutaneous albinism (OCA), that is, TYR mutations cause OCA1, SLC45A2 mutations cause OCA4, and SLC24A5 mutations cause OCA6." (PMID 40741336, 2025). "Among the ion channel and transporters genes involved in pigmentation disorders three are altered in subtypes of oculocutaneous albinism (OCA) (OCA2, SLC45A2, and SLC24A5, in OCA 2, 4 and 6 respectively)." (PMID 39809949, 2025).
oculocutaneous albinism type 4 (17 papers, 2010 to 2025). Oculocutaneous albinism type 4 (OCA4) is a type of OCA characterized by varying degrees of skin and hair hypopigmentation, numerous ocular changes and misrouting of the optic nerves at the chiasm. "The infant also had a homozygous SLC45A2 c.147C>G, p.(Tyr49Ter) variant, which caused oculocutaneous albinism type 4 (OCA4)." (PMID 39282052, 2024). "SLC45A2 mutations cause oculocutaneous albinism type IV (OCA4) and polymorphisms of SLC45A2 gene are associated with dark skin, hair, and eye pigmentation." (PMID 34238381, 2021). "Reduced production of melanin due to genetic mutations in the protein encoded by SLC45A2 results in oculocutaneous albinism type IV (OCA4), an autosomal recessive inherited disorder with reduced melanin pigmentation in skin, hair and eyes." (PMID 29771307, 2018). "Both polymorphisms represent coding variants in the SLC45A2 gene, for which the human equivalent harbors numerous variants associated with oculocutaneous albinism type 4." (PMID 28982372, 2017). "In humans, the predominant allele of SLC45A2 in Europeans, L374F, is clearly not null as it does not cause OCA4; indeed, additional mutations are necessary on this genetic background to cause oculocutaneous albinism type 4 (OCA4)." (PMID 23071798, 2012). "In contrast, rs16891982 represents a non-synonymous amino acid change (F374L) in SLC45A2, and this gene, if mutated, leads to oculocutaneous albinism type IV (MIM# 606574)." (PMID 20886636, 2010). "Wang reported that mutations in the SLC45A2 gene may lead to oculocutaneous albinism type IV (OCA4), while polymorphisms may be linked to darker pigmentation of the skin, hair, and eyes." (PMID 39940926, 2025). "Mutations in SLC45A2 are associated with oculocutaneous albinism type 4 (OCA4)." (PMID 40940787, 2025). "Notably, SLC45A2 is the known pathogenic gene of an autosomal recessive hypopigmentary disorder, oculocutaneous albinism type 4 (OCA4)." (PMID 37627399, 2023). "SLC45A2 mutation leads to oculocutaneous albinism type 4 (OCA4)." (PMID 34722301, 2021). "Also in primates, a mutation in the SLC45A2 gene was indicated to cause the Type 4 Oculocutaneous Albinism (OCA4) phenotype in one specimen of gorilla (Gorilla gorilla)." (PMID 28476152, 2017). "Oculocutaneous albinism type 4 (OCA4) is caused by autosomal recessive mutations in SLC45A2." (PMID 23171239, 2012). "In humans, pathogenic mutations in SLC45A2 lead to type IV oculocutaneous albinism (OCA4)." (PMID 21559390, 2011). "Many studies suggested that Slc45a2 is related to oculocutaneous albinism type IV." (PMID 25790447, 2015).
skin cancer (9 papers, 2008 to 2025). "Further, SLC45A2 rs16891982 has also been associated with tanning response and skin cancer in several studies." (PMID 31315583, 2019). "IRF4 and SLC45A2 are pleiotropic for Category A Phenotypes (skin wrinkling and sagging phenotypes), Category B Phenotypes (skin colour phenotypes), and Category C Phenotypes (skin cancer phenotypes)." (PMID 35907981, 2022). "In skin cancer diagnosis, HSD11B1, SLC45A2, and KRT20 have also been demonstrated to play key roles." (PMID 40917881, 2025). "Firstly, when we compared the genetic correlation, and the MTAG results before and after excluding genomic regions (HLA, ASIP, IRF4, MC1R, SLC45A2 and CDKN2A) with very large effect sizes for skin cancers and pigmentation traits, and there was a high concordance." (PMID 36496446, 2022).
prostate carcinoma (5 papers, 2015 to 2021). A carcinoma that arises from epithelial cells of the prostate gland. "The next most frequent fusion transcripts present in the blood samples from the prostate cancer patients were SLC45A2-AMACR and Pten-NOLC1, accounting for 41.5% (61/147) and 38.8% (57/147), respectively." (PMID 34417538, 2021). "The positive prediction rate for SLC45A2-AMACR in blood versus prostate cancer reached 75% (9/12), while the positive prediction rate for Pten-NOLC1 was 90% (9/10)." (PMID 34417538, 2021). "Eighty-two percent blood samples from the prostate cancer patients were positive for MAN2A1-FER transcript, while 41.5% and 38.8% blood samples from the prostate cancer patients were positive for SLC45A2-AMACR and Pten-NOLC1, respectively." (PMID 34417538, 2021). "SLC45A2-AMACR was also detected in a lung cancer cell line and urothelial carcinoma, in addition to prostate cancer." (PMID 31164957, 2019). "Similar conditions were also found in SLC45A2-AMACR and Pten-NOLC1 fusion: 80% (20/25) SLC45A2-AMACR and 76% (19/25) Pten-NOLC1 were detected in the prostate cancer samples, while the detection rate dropped to 48% (12/25) in the matched blood samples for SLC45A2-AMACR and 40% (10/25) for Pten-NOLC1." (PMID 34417538, 2021). "The high positive prediction rates for MAN2A1-FER (88.2%), SLC45A2-AMACR (75%) and Pten-NOLC1 (90.9%) between blood samples and the primary prostate cancer samples suggests that the source of the fusion transcripts in the blood samples is likely prostate cancer." (PMID 34417538, 2021).
liver cancer (3 papers, 2019 to 2024). An epithelial or non-epithelial malignant neoplasm that arises from the liver. "Fusion genes such as MAN2A1–FER, PTEN–NOLC1, and SLC45A2–AMACR are the oncogenic drivers of liver cancer development." (PMID 38537933, 2024). "Introduction of SLC45A2-AMACR into mouse liver along with somatic knockout of Pten has been shown to induce spontaneous liver cancer in a short period of time." (PMID 38497929, 2024). "In this study, we showed that the fusion transcripts of MAN2A1-FER, CCNH-C5orf30 and SLC45A2-AMACR were detected in the serum samples of liver cancer patients as circulating cell-free RNA." (PMID 31164957, 2019). "To investigate whether targeting SLC45A2-AMACR is feasible in a spontaneous liver cancer model, we constructed an SLC45A2-AMACR cDNA with a full breakpoint intron to mimic the genome structure of SLC45A2-AMACR gene fusion." (PMID 38497929, 2024).
malaria (2 papers, 2014). Malaria is a serious and sometimes fatal disease caused by a parasite that commonly infects a certain type of mosquito which feeds on humans. "These were rs1426654 in SLC24A5 and rs16891982 in SLC45A2, both associated with light skin pigmentation in individuals with European ancestry and rs2814778 in DARC, which encodes the Duffy blood group antigen O allele and is associated with malaria resistance in Africans." (PMID 24980144, 2014).
melanism (2 papers, 2019 to 2025). "Nonetheless, this lack of significant findings in the dominant (GG vs. GT + TT) and recessive (GG + GT vs. TT) alleles supports the absence of any genetic association between the rs11568737 polymorphism of the SLC45A2 gene with melasma in women of African ancestry." (PMID 39940926, 2025). "This novel study reports an absence of single nucleotide polymorphisms of the different genotypes (GG vs. TT, GG vs. GT, and GT vs. TT) for rs11568737 of the SLC45A2 gene in the melasma compared to the control group." (PMID 39940926, 2025). "This study investigates the association between genetic variants in SLC45A2, TYR, HERC2, and SLC24A5 genes and the severity of melasma in women of reproductive age." (PMID 39940926, 2025). "Thus, this study presents a novel investigation into the association of genetic polymorphisms in SLC45A2, TYR, HERC2, and SLC24A5 in African women with melasma, a population that has been under-represented in genetic research on pigmentation disorders." (PMID 39940926, 2025). "By examining polymorphisms in SLC45A2, TYR, HERC2, and SLC24A5, this pilot study highlights the potential genetic factors that may influence melasma susceptibility and severity in a population with distinct pigmentation characteristics." (PMID 39940926, 2025). "However, despite these limitations, this pilot novel study demonstrates valuable insights into melasma development in women of African descent by exploring the genetic role of specific SNPs (SLC45A2, TYR, HERC2, and SLC24A5) in this under-represented population." (PMID 39940926, 2025).
co-infection (1 paper, 2024). "The co-infection induced strong expression of HSV1-tk-mCherry in SLC45A2-AMACR-positive HEPG2 and HUH7 cells, with 98.7 and 95.1% of HEPG2 and HUH7 cells being positive for HSV1-tk-mCherry, respectively." (PMID 38497929, 2024).
keratinocyte carcinoma (1 paper, 2024). A skin cancer arising from the keratin-producing cells of the epidermis. "Most of these genes are pigmentation-related genes (i.e., SLC45A2, TYR, OCA2, MC1R, and ASIP) and have a biological importance of lighter pigmentation in susceptibility to keratinocyte carcinoma." (PMID 38182794, 2024).
rosacea (1 paper, 2018). A chronic erythematous skin disorder that affects the face. "The fourth SNP associated with rosacea symptom severity (rs16891982, P = 1.7 × 10−10) at 5p13 is in the solute carrier family 45 member 2 gene (SLC45A2), which encodes a transporter protein that mediates melanin synthesis with the G allele associated with increased symptom severity." (PMID 29771307, 2018). "This study in individuals of 97% European ancestry has identified significant associations with rosacea genes previously implicated in skin pigmentation (HERC2-OCA2, SLC45A2, IRF4 and MC1R)." (PMID 29771307, 2018).
uveal melanoma (1 paper, 2025). A melanoma derived from melanocytes of the uveal tract. "On the other hand, SLC45A2 encodes a transporter protein that mediates melanin synthesis and shows high expression in uveal melanoma while being present at low levels in normal melanocytes." (PMID 40917881, 2025).
vitamin D deficiency (1 paper, 2023). A nutritional condition produced by a deficiency of VITAMIN D in the diet, insufficient production of vitamin D in the skin, inadequate absorption of vitamin D from the diet, or abnormal conversion of vitamin D to its bioactive metabolites. "Specifically, variants in the SLC45A2 and HERC2-OCA2 loci, together with variants in SLC24A5, were shown to explain a large proportion of variance in skin pigmentation and to associate with vitamin D deficiency in a sample of nearly 600 African Americans." (PMID 37963177, 2023).
X-linked ocular albinism (1 paper, 2019). "Six genes are associated with autosomal recessive OCA (TYR, OCA2, TYRP1, SLC45A2, SLC24A5 and LRMDA), and one gene, GPR143, is associated with X-linked ocular albinism (OA)." (PMID 30679655, 2019).
cancer (13 papers, 2014 to 2026). A tumor composed of atypical neoplastic, often pleomorphic cells that invade other tissues. "The SNP frequencies for AHR (rs2066853) and SLC45A2 (rs26722) gene minor variants (MT) were found to be less than 1.00%; similar findings were published by De Sousa and colleagues related to cancer patients." (PMID 37763073, 2023). "Interestingly, both MFSD12 and SLC45A2 belong to the major facilitator superfamily, which plays important roles in moving compounds across biological membranes and is associated with a variety of cancers." (PMID 30385854, 2019). "Previous studies showed that gene fusion MAN2A1-FER, Pten-NOLC1 and SLC45A2-AMACR are the cancer drivers." (PMID 34417538, 2021). "It is noteworthy that ADAMTS12, AMACR, SLC45A2 and C1QTNF3 are associated with cancers, which are all hallmarked by CIN (aneuploidy)." (PMID 26543751, 2015). "A computer analysed the data and classified them using ML, generating the hypothesis that four of the fusion transcripts (MAN2A1-FER ≤ 40, CCNH-C5orf30 ≤ 38, SLC45A2-AMACR ≤ 41, and PTEN-NOLC1 ≤ 40) were associated with a high probability of cancer." (PMID 39941182, 2025). "SLC45A2-AMACR gene fusion occurs frequently in human cancers." (PMID 38497929, 2024). "Because MUM frequently expresses cancer–testis antigens, such as PRAME or SLC45A2, yet remains immunologically “cold,” TCR-T provides a way to convert antigen expression into a therapeutic weak point." (PMID 41598579, 2026).
tumor (10 papers, 2014 to 2026). "The difference in tumor type in WDPs could be attributable to a true species difference in SLC45A2 function(s), or perhaps due to the effect of a linked variant among the approximately 44 genes in the 10 Mb region of homozygosity surrounding the mutant gene." (PMID 24647637, 2014). "The frequency of the derived allele at rs16891982*G (SLC45A2) was 0.7098 (CI 0.5365–0.8476; N = 15) and at rs1426654*A (SLC24A5) 1 (CI 0.8899–1; N = 15); both are associated with skin depigmentation in Europeans54." (PMID 33980902, 2021). "Therefore, SLC45A2 specific T cells may selectively target tumor cells with less ability to trigger off target toxicities." (PMID 35267523, 2022). "In addition, compared to MART-1 and PMEL-specific T cells, which also show a strong reactivity against HLA-A*02+ primary melanocytes along with tumor cells, SLC45A2-specific T cells target tumors cells had a reduced reactivity against HLA-A2+ primary melanocytes." (PMID 35267523, 2022). "The results showed that their expression levels were positively correlated with SKCM tumor purity (except PMEL, MIA, and SLC45A2)." (PMID 34722301, 2021). "Furthermore, we detected the mRNA expression level of these hub genes in our frozen tissues and found that FAM174B, MAD1L1, MFSD12, SLC45A2, and TBC1D16 were significantly upregulated in freshly frozen tumor tissues." (PMID 30385854, 2019). "We observed a high concordance with immune cell-related but not tumor cell-related genes (NGFR, MITF, MLANA, SLC45A2) and correlation with expression of PDCD1LG2 and SUSD3, irrespective of the side of metastasis." (PMID 38386085, 2024).
SLC45A2 also shares sentences with these, for which no sentence is quoted: basal cell carcinoma (2 papers); Chediak-Higashi syndrome (2); cutaneous malignant melanoma (2); Genetic Disorders (2); Griscelli syndrome (2); Hermansky-Pudlak syndrome (2); non-melanoma skin carcinoma (2); Aland island eye disease (1); Alzheimer disease (1); autosomal recessive inherited disorder (1); autosomal recessive ocular albinism (1); breast carcinoma (1); congenital malformations (1); congenital neutropenia (1); deafness (1); developmental delay (1); diabetic retinopathy (1); eye cancer (1); infection (1); lung carcinoma (1); lysosome-related organelle disorders (1); melanocytic neoplasm (1); Menkes syndrome (1); myxofibrosarcoma (1); nevus (1); Nystagmus (1); ocular albinism (1); oculocutaneous albinism type 1 (1); oculocutaneous albinism type 2 (1); Pigmentary retinopathy (1).
A further 6 diseases each share a sentence with SLC45A2 in 1 paper.